HIF1A (hypoxia inducible factor 1 subunit alpha)
Diseases named in the same sentence as HIF1A in open-access papers (continued):
Sharing a sentence is not in itself a finding about the gene and the disease.
tumor (continued). "Observed in obese patients, alternations of miRNA expression (for example miR-210 and miR-153) influence genes of the hypoxia pathways HIF1A, HK2, and VEGFA during invasion and proliferation of cell culture or tumor breast tissue." (PMID 36555323, 2022). "This, in turn, stabilizes HIF-1α protein, activates the transcription of VEGF, and ultimately accelerates tumor angiogenesis and progression." (PMID 36230880, 2022). "HIF-1α is essential for lactate-mediated activation of GPR81/mTOR/HIF-1α/STAT3 pathway, and inhibition of lactate production in tumor cells or HIF-1α expression in MDSC can restore the immune response of antitumor T cells." (PMID 36686771, 2022). "It was reported that the liposomal -echinomycin can effectively inhibit HIF-1α transcriptional activity of primary and metastatic TNBC cells and inhibit tumor growth in vivo." (PMID 36003773, 2022). "Mice treated with doxorubicin had lower expression of tumor HIF-1α and HIF-2α than did controls, and those treated with doxorubicin plus FO/Se expressed significantly lower levels of HIF-1α and HIF-2α protein than did those treated with doxorubicin alone." (PMID 36483592, 2022). "Collectively, our results reveal that hypoxia-induced circRNF13 mediated by HIF-1α and EIF4A3 promotes tumor progression and glycolysis in PC, indicating the potential of circRNF13 as a prognostic biomarker and therapeutic target for PC." (PMID 36369467, 2022). "mPRα knockdown or overexpression was generated in LUAD cells, and the roles of mPRα in cAMP concentrations, the protein levels of STAT3 signaling factors, HIF1α, and VEGF, and LUAD cell migration, invasion in vitro and tumor growth in vivo were investigated." (PMID 35123491, 2022). "In vivo analysis showed that knockout of HIF‐1α and/or Glut‐1 also inhibited tumour growth by promoting cell apoptosis, more robustly compared with the PI3K inhibitor wortmannin, particularly in tumours with knockout of both HIF‐1α and Glut‐1." (PMID 35415942, 2022). "Mechanistically, Myo1b blocked the autophagic degradation of HIF-1α and then led to the accumulation of HIF-1α, thus enhancing VEGF secretion and then promoting tumor angiogenesis in CRC." (PMID 36347835, 2022). "HIF-1a and hypoxia are recognized drivers of epithelial-mesenchymal transition (EMT), a process that induced tumor metastasis." (PMID 35392964, 2022). "For a fraction of the cohort, IHC staining of HIF-1α in matched primary and IBTR tumour material was available (n = 119)." (PMID 35140341, 2022). "Thus, HIF-1α drives the conversion from oxidative to glycolytic metabolism during hypoxia, which is not only beneficial for bioenergetic homeostasis, but may also promote tumor survival and growth." (PMID 36408139, 2022). "Our scRNA-seq data confirmed a fivefold reduction in GPx2 mRNA in the GPx2 KD tumor and violin plots confirmed a dramatic increase in HIF1α and VEGFA mRNAs in most of the clusters that make up the GPx2 KD tumor." (PMID 35193955, 2022). "These authors found that HIF-1α and c-Myc expression detected by immunohistochemistry could add to the development of a prognostic nomogram together with the histological grade and stage of cancer (based on tumor size (T), lymph node involvement (N) and distant metastases (M), known as TNM status)." (PMID 35629169, 2022). "HIF-1α induces vascular target genes, and VEGF is the main target to induce tumor angiogenesis and improve blood flow in inflammatory reaction sites or tumor tissues." (PMID 35493517, 2022). "Enrichment of HIF-1α and autophagy-related signaling pathways was also observed, indicating an alteration in the MCF-7SC tumor environment, as HIF-1α is involved in the regulation and maintenance of CSCs in hypoxic microenvironments." (PMID 35631492, 2022).
tumor (continued). "HIF1α was identified as a transcription factor of numerous genes related to the EMT, stem-like properties and metastasis of tumor cells, including Twist1, ZEB1 and ZEB223,24,43." (PMID 35941273, 2022). "These signaling pathways can also induce the expression of HIF-1α, TNF-α, IL-10, TGF-β, and other factors to inhibit the anti-tumor immune response." (PMID 35620732, 2022). "We suggest an alternative perspective to explicate the role of HIF-1α and HIF-2α in tumor progression." (PMID 35267567, 2022). "HIF-1α, as one of the HIF family members, is critically related to tumor metastasis and tumor staging." (PMID 36329448, 2022). "Notably, the hypoxia-induced transactivation of HIF-1α has been associated with an increase in the expression of metalloproteinase ADAM10 and a decrease in the surface MHC class I chain-related (MIC) levels, further highlighting the resistance of tumor cells to innate immune-mediated lysis." (PMID 35681654, 2022). "After sulforaphane treatment, the STAT3/HIF‐1α/VEGF pathway was blocked and the angiogenesis and tumor growth were inhibited." (PMID 35356799, 2022). "Given that both HIF1α and ATF4 are activated by distinct forms of metabolic and cellular stress, these data further point to how distinct tumor types are dependent on different types of stress signaling." (PMID 35019856, 2022). "Consistently, IHC analysis revealed that swimming significantly downregulated CD31, HIF-1α, VEGFA, and VEGFR2 protein expression in tumor tissues." (PMID 35291563, 2022). "HIF-1α can upregulate HOTAIR, NEAT1, UCA1, MALAT1, H19, and LincROR in tumor cells by specifically binding to the HREs of their promoter." (PMID 35387966, 2022). "Contrarily to HIF-1α, relatively little has been revealed on the role of HIF-2α in tumor immune response, although HIF-2α has been known to be implicated in the immunosuppressive functions of TAM." (PMID 35805044, 2022). "Tumor-derived lactate promotes MDSCs induction and activation through the GPR81/HIF-1α/STAT3 signaling pathway, suggesting the role of enhanced lactate secretion as a mechanism of radioresistance." (PMID 36713558, 2022). "HIF-1α is an important regulator of VEGFA expression in local hypoxia, such as tumor microenvironment and on the development and survival of the hematopoietic system." (PMID 35634304, 2022). "In conclusion, DFO inhibited the proliferation and ALL xenograft tumor growth, obstructed the cell cycle, and induced apoptosis of ALL cells, probably via inactivating the ROS/HIF-1α, Wnt/β-catenin, and p38MAPK/ERK signaling." (PMID 35237325, 2022). "In fact, both HIF-1α and HIF-2α play important roles in tumor angiogenesis, survival, proliferation, immune evasion, plasticity, invasion and metastasis, chemo- and radio-therapy resistance, pH regulation, and metabolism." (PMID 35774228, 2022). "This suggests that the functions of HIF-1α and HIF-2α are plastic during tumor progression, play an important regulatory role in the metabolic reprogramming of tumor cells and macrophages, and produce interesting changes under the influence of TME." (PMID 35874739, 2022). "At the same time, the platform released sunitinib and active oxygen to induce apoptosis and inhibit tumor angiogenesis, with increased expression of cleaved PARP and decreased levels of VEGFA, HIF-1α, survivin, and p-STAT3." (PMID 35784750, 2022). "Toward endometrial cancer, the effect of the prodrug of EGCG (ProEGCG) exhibited anti-proliferative, pro-apoptotic, and anti-tumor actions via ERK/JNK, Akt and PI3K/AKT/mTOR/HIF1α signaling pathway." (PMID 35860020, 2022).
tumor (continued). "Because EMT, HIF-1α/VEGF, and PI3K/AKT signaling pathways tightly regulate tumor migration and invasion, we evaluated EMT progress by measuring the protein expression levels of Twist, E-Cadherin, and Smad2 in DLD1 cells." (PMID 35860704, 2022). "Because HIF1α protein is highly expressed in hypoxic regions, this result indicates that SQAP induced reoxygenation of the tumor tissues." (PMID 34738103, 2022). "For expression of HIF-1α, EGFR, pAKT and pMAPK, tumor samples were analyzed by immunohistochemistry in tissues microarrays." (PMID 36358811, 2022). "The PI3K/AKT/mTOR axis also regulates hypoxia-inducible factor 1-alpha (HIF-1α) mediated expression of VEGF, leading to the vascularization of the tumor, supporting a role for AKT in the development and maintenance of the PVN stem cell niche." (PMID 35747808, 2022). "Both the RT-PCR and western blot results indicate that HIF1α is oncogenic and upregulated when the Redox and Krebs oncometabolites are also highly expressed in CML; on the other hand, Notch1 behaves like a tumor suppressor in CML cases." (PMID 35847841, 2022). "We also observed that USP2-AS1 knockdown decreased the transcript level of some downstream target genes of HIF1α under hypoxia, such as MAPK1, VEGF, MDR1(ABCB1), GLUT1, whose transcriptional activation play an important role in tumor hypoxia metabolism." (PMID 35692750, 2022). "Three markers (HIF-1α, VEGF, and CD31) were used to assess the tumor microenvironment on Day 7 after TAE therapy." (PMID 36510170, 2022). "By staining the tumor tissue sections, we observed that ARS and 231M-AP NPs decreased HIF-1α expression and significantly attenuated hypoxia in solid tumors." (PMID 36382024, 2022). "Western blotting data for tumor tissues showed that chrysin treatment decreased SPHK-1, HIF-1α, and PARP expression while inducing caspase-3 cleavage." (PMID 36139362, 2022). "The data also demonstrates that elevated HIF-1α is correlated with clinicopathological features such as LNM, DM, advanced TNM stage, and larger tumor size in digestive system cancers." (PMID 35845307, 2022). "PTBP3 can promote colorectal cell proliferation, migration, and invasion in vitro and tumour growth and metastasis in vivo by binding to the 5′UTR HIF-1α mRNA to enhance HIF-1α protein expression." (PMID 35359851, 2022). "In renal cell carcinoma, hypoxia-induced HIF-1α enhances ALKBH5 expression, which, in turn, promotes tumor proliferation through increasing the percentage of cells in the G2/M phase." (PMID 35794625, 2022). "Hypoxia can inhibit the function of HIF-PH and activate the HIF1A pathway, which increases the expression of molecules such as VEGF and promotes tumor angiogenesis." (PMID 35745653, 2022). "In normoxia, HIF-1α is degraded, and the reports by Ratcliffe and Kaelin showed that prolyl hydroxylases (PHDs) and von Hippel-Lindau (VHL), a tumor suppressor, play important roles in this process." (PMID 35563687, 2022). "In any case, our study identified a new regulator of the HIF1α signaling pathway, RBCK1, which can modulate tumor progression in ER-positive breast cancer cells by modulating this pathway, providing a new target for the treatment of ER-positive breast cancer." (PMID 36473847, 2022). "Genes associated with epithelial-to-mesenchymal transition (EMT) such as HIF-1a, HOTAIR, SLUG, and ZEB1 are targets of this tumor suppressor miRNAs." (PMID 35454102, 2022). "In renal cancer carcinoma, HIF-1α and HIF-2α have opposite effects, HIF-1α being a tumor suppressor, and HIF-2α acting as an oncogene." (PMID 35269613, 2022). "Among these agents, the monoclonal antibody cetuximab (C225) decreased HIF-1α levels and VEGF-A production in in vitro and in vivo tumor models." (PMID 35158804, 2022).
tumor (continued). "HIF1A and TGF-β2 jointly activate the tumor resistance gene GLI2, enhancing intrinsic tumor resistance to chemotherapeutic drugs." (PMID 35659268, 2022). "LMP1 can activate PI3K/AKT and HIF-1α signaling pathways in EBV-positive NPC cells and function in chemokine ligand 5- (CCL5-) mediated tumor angiogenesis." (PMID 36438903, 2022). "Previous studies have reported that the expression of HIF-1α and its transcription target CAIX increases in tumor cells under hypoxia." (PMID 35957825, 2022). "The IHC and western blotting results showed that expression levels of COMMD3, HIF1α, VEGF and CD34 proteins in xenograft tumours from LV-Con group were significantly higher than those from LV-ShCOMMD3 group." (PMID 35399735, 2022). "Under hypoxic conditions, HIF1A induces, among others, angiogenesis, the program of EMT, and proliferation, as well as the migration of tumor cells." (PMID 36613607, 2022). "The treatment with the tumor soil loosening agent combined with the PD1 inhibitor significantly decreased the expression of DDR1, HIF-1α, MMP-14, and α-SMA." (PMID 36382024, 2022). "Further work in this area led to the discovery of hypoxia-inducible factor 1 alpha (Hif1α) and vascular endothelial growth factor (VEGF) whose expressions in concert drive angiogenesis, energy metabolism, and tumor cell invasion." (PMID 35216362, 2022). "A previous study demonstrated that HIF1α stabilized by Lysine-specific demethylase 1 cooperates with CBP and MTA1 to enhance VEGF induced tumor angiogenesis." (PMID 35355718, 2022). "The experiments in vitro demonstrated that PHD-3 can act as a downregulator of HIF-1α and VEGF that are involved in tumor angiogenesis." (PMID 35330327, 2022). "This phosphorylation activates HIF1α and VEGF and the expression of CCL5 in LECs (Lymphatic Endothelial Cells), directing the spread of the tumor to other tissues." (PMID 36497411, 2022). "Hypoxia can stimulate HIF-1α, and HIF-1α, in turn, enhances the expression of genes involved in glycolysis (GLUT1) and angiogenesis (VEGF), promoting tumor growth." (PMID 36551599, 2022). "Under hypoxic conditions such as a tumor, VHL cannot bind to HIF1α, with HIF1α activating genes whose products promote angiogenesis, e.g., VEGF and PDGFβ, as well as regulating glucose metabolism." (PMID 35136485, 2022). "Aside, it was demonstrated that the deletion of Hif1a in T cells before transfer leads to an enhanced FAO activity and increases the anti-tumor activity of T cells." (PMID 35682650, 2022). "Over production of HIF1α in the TME increases BCL9 expression, mediating activation of β-catenin-mediated transcriptional activity at hypoxic tumor tissues, and facilitates VM." (PMID 35757736, 2022). "We went on to confirm the correlation among CA12, HIF1α, and cytokine expression in HCC tumor tissue–purified CD14+ cells." (PMID 35362480, 2022). "Then, we analyzed the histoscores of Hsp70, Hif1α, cortactin MMP14, and MMP2 in both tumor and normal tissues and observed significantly higher expression levels of these proteins in OSCC tissues." (PMID 35957827, 2022). "Lactate has been reported to be absorbed by tumor cells and subsequently converted to pyruvate, which directly competes with α-KG to inhibit the activity of PHD, thereby stabilizing HIF-1α levels." (PMID 36050306, 2022). "Mechanistic studies suggested that miRNAs promote tumor responses to hypoxia and angiogenesis by repressing FIH1, an inhibitor of HIF-1α." (PMID 35918758, 2022). "The improved efficacy is attributed to the targeted delivery of 17-AAG to tumor tissues, which not only inhibited the PDT/PTT-induced HIF-1α, but also down-regulated several cancer-promoting signaling molecules, such as Akt, Src and Erk in BC." (PMID 36195918, 2022).
tumor (continued). "By increasing the levels of several factors (e.g., HIF-1α, HGF, EGF, TGF-β, TNF-α, TPA, MMP-3, and even micro-RNA), ROS can enhance and help the EMT and promote the metastasis of tumor cells." (PMID 35659296, 2022). "Acriflavine binds to the PAS-B domain of HIF-1α, blocking its interaction with HIF-1β, which leads to the suppression of tumor growth and tumor vascularization." (PMID 36551540, 2022). "In line with this reasoning, we further confirmed that BMP receptor inhibitors successfully suppressed tumor growth, as well as ID1, HIF-1α, VEGFA, and VEGFR2 expression in HCC xenograft tumors." (PMID 35163396, 2022). "Our results demonstrated that 6-gingerol treatment inhibited HIF-1α target genes, including MMP-9, vimentin and snail, which are correlated with tumor metastasis." (PMID 35408505, 2022). "The SB lessened tumor angiogenesis in pancreatic cancer and prostate tumor xenograft, while SB inhibited tumor angiogenesis via restricting VEGF, VEGFR2, HIF-1α, and iNOS expression in a transgenic mouse of prostate cancer." (PMID 35784750, 2022). "The activation of hypoxia-inducible factor-1α (HIF-1α) by tumour hypoxia strongly activates the secretion of the SHH ligand by cancer cells, which promotes proliferation and tumour survival." (PMID 36291078, 2022). "HIF1A is a promising therapeutic candidate in OCCC because of its important role in chemotherapy resistance, tumor metastasis, angiogenesis, and immunosuppression." (PMID 35565252, 2022). "PMA stimulation was revealed to significantly upregulate tumor PD-1 expression in a manner that involved NFκB, JNK, and HIF-1α signaling, and this was faithfully represented by increased 89Zr-PD-1 IgG binding in vitro and enhanced tumor uptake in vivo." (PMID 35250391, 2022). "Consistent with the tumor volume data, SIRT6, HIF-1α, HK2 and Ki-67 protein levels were lower in the PC9/ER/shSIRT6 tumor tissue samples than in the PC9/ER/shCtrl tissue samples." (PMID 35915188, 2022). "Compound 6b inhibited angiogenesis, tumor progression, metabolic reprograming, and metastasis by inhibiting EGFR by decreasing Hif-1α expression upon treatment." (PMID 36080307, 2022). "Tumour expression of angiogenesis promotor proteins like VEGF, interleukin-8 (IL-8) and HIF-1α leads to the formation of a heterogeneous, leaky and highly branched tumour vasculature." (PMID 35897938, 2022). "Consistent with this, the present in vivo data indicated that ablating HIF-1α by silencing Notch1 as a guard-molecule or by treating with chetomin, a HIF pathway inhibitor, induced significant anti-tumor effects in GBM xenograft models." (PMID 36183290, 2022). "Of note, in Kaposi sarcoma cells, IFG-I-mediated induction of HIF-1α, HIF-2α, and VEGF-A was lessened by inhibiting IGF-IR, leading to decreased tumor vascularization." (PMID 35158804, 2022). "Hyaluronic acid-coated mannan-conjugated MnO2 particles (Man-HA-MnO2) treatment of a breast tumor mouse model has been shown to significantly increase tumor oxygenation and downregulation of HIF-1α and VEGF in the tumor." (PMID 35163420, 2022). "Another interesting finding was the significant association of the overexpression of three hypoxia and acidity-related markers, namely, HIF1α, HIF2α, and CA9, with an immunologically cold tumor microenvironment." (PMID 35735451, 2022). "eATP increases tumor cell survival and drug resistance by increased glucose transporter 1 (GLUT1) expression through the P2X7R-PI3K-Akt and hypoxia-inducible factor 1α (HIF-1α)." (PMID 36072596, 2022). "The key mechanism identified in this study involved an anticancer mechanism that regulates tumor growth, VM, tumor proliferation, apoptosis, and reactive oxygen species (ROS) by inhibition of the SPHK-1/HIF-1α pathway." (PMID 36139362, 2022).